MMAA (metabolism of cobalamin associated A)
Description:
GTPase, binds and hydrolyzes GTP. Involved in intracellular vitamin B12 metabolism, mediates the transport of cobalamin (Cbl) into mitochondria for the final steps of adenosylcobalamin (AdoCbl) synthesis. Functions as a G protein chaperone that assists AdoCbl cofactor delivery from MMAB to the methylmalonyl-CoA mutase (MMUT). Plays a dual role as both a protectase and a reactivase for MMUT. Protects MMUT from progressive inactivation by oxidation by decreasing the rate of the formation of the oxidized inactive cofactor hydroxocobalamin (OH2Cbl). Additionally acts a reactivase by promoting the replacement of OH2Cbl by the active cofactor AdoCbl, restoring the activity of MMUT in the presence and hydrolysis of GTP.
Synonyms: cblA; LINC02491
Tractability: Small molecule: a structure with a bound ligand is known; it has a binding pocket of medium quality. PROTAC: ubiquitination databases record sites on it; its protein half-life has been measured.
Gene: Protein-coding gene on chromosome 4 (145,599,042 to 145,660,033, forward strand). Ensembl gene ENSG00000151611.
Subcellular location: Mitochondrion; Cytoplasm
Subcellular location (Human Protein Atlas): Cytosol
Pathways (Reactome):
Disease: Defective MMAA causes MMA, cblA type; Defective MUT causes MMAM
Metabolism: Cobalamin (Cbl) metabolism; Propionyl-CoA catabolism
Gene Ontology:
Molecular function: GTP binding; GTPase activity; identical protein binding; molecular carrier activity; protein binding; protein homodimerization activity
Biological process: cobalamin metabolic process
Cellular component: cytoplasm; cytosol; mitochondrion; mitochondrial matrix
Genetic constraint (gnomAD): Loss-of-function variants: 43 observed, 47.97 expected, observed/expected ratio (o/e) 0.9, 90% interval 0.7 to 1.16. The upper end of that interval is the gene's LOEUF score, 1.16, which puts it in group 5 of 6, group 1 being the genes least tolerant of losing a copy. Missense variants: 460 observed, 524.05 expected, observed/expected ratio (o/e) 0.88, 90% interval 0.81 to 0.95. Synonymous variants: 154 observed, 189.34 expected, observed/expected ratio (o/e) 0.81, 90% interval 0.71 to 0.93.
Gene-disease validity (ClinGen):
ClinGen rates the evidence that MMAA causes each of these diseases.
methylmalonic aciduria, cblA type (autosomal recessive): Definitive. An autosomal recessive form of methylmalonic aciduria, caused by mutation(s) in the MMAA gene, encoding MMAA protein.
Homologues: Orthologues: chimpanzee MMAA (99% identical), macaque MMAA (98% identical), pig MMAA (91% identical), dog MMAA (88% identical), guinea pig MMAA (88% identical), rabbit MMAA (85% identical), mouse Mmaa (79% identical), rat Mmaa (79% identical), tropical clawed frog mmaa (66% identical), zebrafish mmaa (62% identical), Caenorhabditis elegans mmaa-1 (43% identical). Paralogues in human: MMUT (23% identical).
Diseases named in the same sentence as MMAA in open-access papers:
MMAA is named in the same sentence as 21 diseases in open-access papers, as found by Europe PMC text mining. Sharing a sentence is not in itself a finding about the gene and the disease. The quoted sentences say what the papers report.
Methylmalonic aciduria (9 papers, 2013 to 2024). Increased concentration of methylmalonic acid in the urine. "One of the causes of the disease is the methylmalonic aciduria, cblA type (cblA - type MMA), conditioned by a mutation in the MMAA gene, which is essential for the proper functioning of a cofactor of the methylmalonyl-CoA mutase." (PMID 31921599, 2020). "In the Ketosis example, only two diseases were associated with onset data: Methylmalonic aciduria, cblA type (caused by MMAA) annotated as both ‘neonatal’ and ‘infantile’ and Glycogen storage disease IXc (caused by PHKG2) which also an infantile disease according to HPO." (PMID 28715999, 2017). "Mutations in MMAA, MMAB, and MUT (corresponding to cblA, cblB, and mut complementation groups) are associated with isolated methylmalonic aciduria, while mutations in MTRR and MTR (corresponding to cblE and cblG complementation groups) are associated with isolated homocystinuria." (PMID 38203763, 2024).
methylmalonic acidemia (6 papers, 2014 to 2025). A genetically heterogenous inherited disorder characterized by abnormalities in the metabolism of lipids and proteins. "By contrast, methylmalonic acidemia, cblA-type, (MMAA) has a carrier rate of 1 in 600 and 13observed pathogenic variants, giving a median estimated clinical detection rateof 85%." (PMID 30816298, 2019). "Methylmalonic acidemia, cblA type, is an inborn error of vitamin B12 metabolism that occurs due to mutations in the MMAA gene." (PMID 28536607, 2016).
End Stage Renal Disease (1 paper, 2021). "We report the case of a 10-year-old girl, born to a patient affected by CblA (homozygous pathogenic mutation c.586C>T (p.Arg196Term) in exon 4 of the MMAA gene) complicated with End Stage Renal Disease (ESRD) and renal transplantation at 16 years of age." (PMID 34828726, 2021).
MMAA also shares sentences with these, for which no sentence is quoted: homocystinuria (4 papers); propionic acidemia (3); cobalamin deficiency (2); Optic neuropathy (2); Acute encephalopathy (1); cancer (1); Chronic colitis (1); colitis (1); glycogen storage disease IXc (1); Hyperammonemia (1); infection (1); megaloblastic anemia (1); metabolic disorder (1); mitochondrial DNA depletion syndrome (1); MTHFR deficiency (1); renal disease (1); tumor (1); Vitamin B12 (1).